SLC7A7 (solute carrier family 7 member 7)
Description:
Heterodimer with SLC3A2, that functions as an antiporter which operates as an efflux route by exporting cationic amino acids from inside the cells in exchange with neutral amino acids plus sodium ions and may participate in nitric oxide synthesis via the transport of L-arginine. Also mediates arginine transport in non-polarized cells, such as monocytes, and is essential for the correct function of these cells. The transport mechanism is electroneutral and operates with a stoichiometry of 1:1 (By similarity). In vitro, Na(+) and Li(+), but also H(+), are cotransported with the neutral amino acids (By similarity).
Synonyms: MOP-2; Y+LAT1; y+LAT-1; LAT3; LPI
Tractability: Small molecule: a structure with a bound ligand is known. Antibody: UniProt places it where antibodies can reach, with high confidence; its Gene Ontology location is reachable by antibodies, with high confidence; UniProt predicts a signal peptide or a membrane-spanning region.
Gene: Protein-coding gene on chromosome 14 (22,773,222 to 22,829,820, reverse strand). Ensembl gene ENSG00000155465.
Subcellular location: Basolateral cell membrane
Pathways (Reactome):
Disease: Defective amino acid transport by SLC7A7 causes lysinuric protein intolerance (LPI)
Hemostasis: Basigin interactions
Transport of small molecules: Amino acid transport across the plasma membrane
Gene Ontology:
Molecular function: protein binding; basic amino acid transmembrane transporter activity; L-amino acid transmembrane transporter activity; L-arginine transmembrane transporter activity; transmembrane transporter activity
Biological process: amino acid import across plasma membrane; L-arginine transmembrane transport; L-leucine transport; amino acid transmembrane transport; basic amino acid transmembrane transport; transmembrane transport
Cellular component: basolateral plasma membrane; transmembrane transporter complex; plasma membrane; membrane
Genetic constraint (gnomAD): Loss-of-function variants: 38 observed, 49.44 expected, observed/expected ratio (o/e) 0.77, 90% interval 0.59 to 1.01. The upper end of that interval is the gene's LOEUF score, 1.01, which puts it in group 4 of 6, group 1 being the genes least tolerant of losing a copy. Missense variants: 584 observed, 664.61 expected, observed/expected ratio (o/e) 0.88, 90% interval 0.82 to 0.94. Synonymous variants: 234 observed, 255.11 expected, observed/expected ratio (o/e) 0.92, 90% interval 0.82 to 1.02.
Gene-disease validity (ClinGen):
ClinGen rates the evidence that SLC7A7 causes each of these diseases.
lysinuric protein intolerance (autosomal recessive): Definitive. Lysinuric protein intolerance (LPI) is a very rare inherited multisystem condition caused by disturbance in amino acid metabolism.
Homologues: Orthologues: chimpanzee SLC7A7 (100% identical), macaque SLC7A7 (98% identical), pig SLC7A7 (93% identical), rabbit SLC7A7 (92% identical), rat Slc7a7 (91% identical), guinea pig SLC7A7 (90% identical), mouse Slc7a7 (90% identical), tropical clawed frog slc7a7 (80% identical), zebrafish slc7a7 (72% identical), Drosophila melanogaster mnd (45% identical), dog SLC7A7 (45% identical), Drosophila melanogaster CG1607 (42% identical), and 9 more. Paralogues in human: SLC7A6 (71% identical), SLC7A5 (47% identical), SLC7A8 (46% identical), SLC7A10 (42% identical), SLC7A11 (41% identical), SLC7A9 (39% identical), SLC7A13 (28% identical), SLC7A2 (24% identical), SLC7A3 (24% identical), SLC7A1 (24% identical), SLC7A4 (22% identical), SLC7A14 (19% identical).
Diseases named in the same sentence as SLC7A7 in open-access papers:
SLC7A7 is named in the same sentence as 81 diseases in open-access papers, as found by Europe PMC text mining. Sharing a sentence is not in itself a finding about the gene and the disease. The quoted sentences say what the papers report.
lysinuric protein intolerance (37 papers, 2010 to 2026). "Mutations in SLC7A7 cause lysinuric protein intolerance (LPI), and this gene has been implicated in monogenic lupus." (PMID 41821046, 2026). "Lysinuric protein intolerance is a rare autosomal disorder caused by mutations in the Slc7a7 gene that lead to impaired transport of neutral and basic amino acids." (PMID 39881295, 2025). "Molecular testing revealed two pathogenic variants in SLC7A7, confirming his diagnosis of lysinuric protein intolerance." (PMID 41189639, 2025). "Lysinuric protein intolerance (LPI) is an autosomal recessive disorder caused by mutations in the SLC7A7 gene, which encodes the Y+L Amino Acid Transporter 1, impairing the transport of cationic amino acids." (PMID 40428338, 2025). "Defects in SLC7A7 (encoding a subunit of a cationic amino acid transporter) can lead to lysinuric protein intolerance (LPI) and SLE." (PMID 38420886, 2024). "Lysinuric protein intolerance is a rare inherited metabolic disease due to autosomal recessive mutations of the SLC7A7 gene." (PMID 37528333, 2023). "For instance, an 11-month-old girl was diagnosed with matUPD14 and a homozygous mutation of the SLC7A7 gene located 14q11.2, leading to lysinuric protein intolerance (LPI)." (PMID 37860673, 2023). "Trio-exome sequencing showed a mutation c.625 + 1G > A in the SLC7A7 gene compatible with fetal Lysinuric protein intolerance (LPI)." (PMID 33784964, 2021). "Lysinuric protein intolerance (LPI) is a rare primary inherited aminoaciduria caused by biallelic mutations in the SLC7A7 gene, which encodes the HAT light chain y+LAT1." (PMID 31878022, 2019). "Lysinuric protein intolerance (LPI) is a rare metabolic disease resulting from recessive-inherited mutations in the SLC7A7 gene encoding the cationic amino-acids transporter subunit y+LAT1." (PMID 28057010, 2017). "Variants in SLC7A7 are associated with lysinuric protein intolerance." (PMID 41296379, 2025). "Indeed, mutations in SLC7A9 (b0,+AT) lead to cystinuria (MIM 220100), whereas mutations in SLC7A7 (y + LAT1) result in lysinuric protein intolerance (LPI) (MIM 222700)." (PMID 34436365, 2021). "We performed a proband-only exome and detected two homozygous mutations in two different genes: MAN2B1 (Mannosidase Alpha Class 2B Member 1) and SLC7A7 (Solute Carrier Family 7 Member 7), in which mutations cause alpha-mannosidosis and lysinuric protein intolerance respectively." (PMID 31362757, 2019). "To finally explore the potential relationship between PBA and LCN2 in humans, we took advantage of a patient followed in our nephrology department for a lysinuric protein intolerance (a urea cycle disorder due to a SLC7A7 gene mutation), which was associated with amyloidosis and proteinuria." (PMID 26787103, 2016). "Lysinuric protein intolerance is associated with mutation in SLC7A7 gene." (PMID 25029527, 2014). "In contrast, the almost exclusive presence of the mutated y + LAT1 (SLC7A7) in others would be the reason for the onset of Lysinuric protein intolerance (LPI) complications." (PMID 41142409, 2025). "Solute transport family 7A member 7 (SLC7A7) mutations contribute to lysinuric protein intolerance (LPI), which is the mechanism of action that has been extensively studied." (PMID 39730571, 2024). "SLC7A7 deficiency, or lysinuric protein intolerance (LPI), causes loss of function of the y+LAT1 transporter critical for efflux of arginine, lysine and ornithine in certain cells." (PMID 37486182, 2023). "Lysinuric protein intolerance (LPI) is a rare inherited metabolic disease resulting from autosomal recessive mutations involving the SLC7A7 gene." (PMID 37528333, 2023). "SLC7A7 mutations contribute to lysinuric protein intolerance (LPI), whose symptoms compose of growth retardation, muscle hypotonia and hepatosplenomegaly." (PMID 34512655, 2021).
lysinuric protein intolerance (continued). "Lysinuric protein intolerance (LPI) is a rare autosomal disease caused by defective cationic amino acid (CAA) transport due to mutations in SLC7A7, which encodes for the y+LAT1 transporter." (PMID 31653080, 2019). "Lysinuric protein intolerance (LPI) is a recessively inherited aminoaciduria caused by mutations of SLC7A7, the gene encoding y+LAT1 light chain of system y+L for cationic amino acid transport." (PMID 29616026, 2018). "In the recessive aminoaciduria Lysinuric Protein Intolerance (LPI), mutations of SLC7A7/y+LAT1 impair system y+L transport activity for cationic amino acids." (PMID 21110863, 2010). "Mutations in the SLC7A7 gene are known to cause lysinuric protein intolerance (LPI)." (PMID 41142409, 2025). "For instance, lysinuric protein intolerance (LPI), an inherited rare disease caused by mutations in SLC7A7 gene (coding for the CAAT called y+LAT1) is notably known to considerably decrease the CAA flux across the intestine." (PMID 38318367, 2024). "Lysinuric protein intolerance (LPI), caused by pathogenic variants of SLC7A7, is characterized by protein aversion, failure to thrive, hyperammonemia, and hepatomegaly." (PMID 37927490, 2023). "Lysinuric protein intolerance (LPI) is a rare inborn error of metabolism (IEM), classified as an inherited aminoaciduria, caused by mutations in the SLC7A7 gene, leading to a defective cationic amino acid transport." (PMID 37835050, 2023). "Lysinuric protein intolerance (OMIM 222700) is most prevalent in the Finnish population and has been associated with mutations in SLC7A7." (PMID 31679053, 2019). "Lysinuric protein intolerance (LPI; MIM 222700) is a recessively inherited aminoaciduria caused by mutations of SLC7A7, the gene encoding y+LAT1 light chain of system y+L for cationic amino acid transport." (PMID 29616026, 2018). "The hematopoietic defects in the Lysinuric protein intolerance mouse model are not caused by intrinsic Slc7a7 loss in hematopoietic cells but rather by impaired erythropoietin production in the kidney." (PMID 39881295, 2025). "Lysinuric protein intolerance [LPI; Online Mendelian Inheritance in Man (OMIM) #222700] is an inborn error of cationic amino acid transport caused by biallelic pathogenic variants in SLC7A7 that results in loss of function of the y+LAT1 transporter." (PMID 37486182, 2023). "Lysinuric protein intolerance (LPI; OMIM #222700) is a rare inborn metabolic disease resulting from recessive-inherited mutations involving the SLC7A7 gene." (PMID 28057010, 2017). "Lysinuric protein intolerance (LPI) is a rare autosomal recessive disorder of AA transport caused by mutations in the SLC7A7 gene, coding for the y+L amino acid transporter 1 (y+LAT1), which transfers cationic AAs Orn, Arg, and Lys from the cell to the extracellular space." (PMID 40428324, 2025). "Lysinuric protein intolerance (LPI, MIM222700) is a rare autosomal recessive disorder caused by defective cationic amino acid (CAA) transport due to mutations in SLC7A7, which encodes for the y+LAT1 protein." (PMID 31653080, 2019). "Lysinuric protein intolerance (LPI), a condition in which reduced activity of the cationic amino acid transporter SLC7A7 leads to reduced intestinal uptake and increased urinary loss of amino acids, is associated with frank osteoporosis and an increased fracture rate." (PMID 30209646, 2018).
glioblastoma (5 papers, 2020 to 2024). The most malignant astrocytic tumor (WHO grade IV). "The gene mutations of the amino acid transport protein SLC7A7 have been confirmed to be the risk factors for the development of tumors, including glioblastoma." (PMID 38291499, 2024). "It has been proved that glioblastoma overexpressed SLC7A7 compared to normal brain tissue, and overexpression of SLC7A7 was correlated with poor prognosis in glioblastoma." (PMID 37214463, 2023). "SLC7A7 was a significant and independent biomarker for predicting poor prognosis and was a potential prognosis predicter of glioblastoma." (PMID 33384961, 2020). "Overexpression of SLC7A7 is correlated with poor prognosis in patients with glioblastoma." (PMID 36119478, 2022). "Univariate analyses also demonstrated that SLC7A7 and ASS1 were hazardous prognostic factors for glioblastoma, while DDAH1 and NOS1 were proved as protective factors for glioblastoma." (PMID 37214463, 2023). "Overexpression of SLC7A7 is correlated with poor RFS and OS in patients with glioblastoma." (PMID 33632211, 2021). "SLC7A7 has been investigated at the single-cell level in nine types of cancer, including AML (acute myeloid leukemia), ALL (acute lymphoblastic leukemia), CML (chronic myelogenous leukemia), GBM (glioblastoma), LUAD, MEL (melanoma), RCC (renal cell carcinoma), BRCA and PC (prostate cancer)." (PMID 33632211, 2021).
non-small cell lung carcinoma (5 papers, 2014 to 2025). A group of at least three distinct histological types of lung cancer, including non-small cell squamous cell carcinoma, adenocarcinoma, and large cell carcinoma. "Mounting evidence showed dysregulation of SLC7A7 was associated with resistance of chemotherapy and radiation in ovarian cancers and non-small cell lung cancer, respectively." (PMID 33384961, 2020). "In non-small-cell lung carcinoma, SLC7A7 expression positively correlates with the level of immune infiltration." (PMID 40075158, 2025). "Deregulation of the amino acid transporter Slc7a7 is involved in multiple types of cancer, including gliobastoma, non-small cell lung cancer and multiple myeloma." (PMID 25038616, 2014). "SLC7A7 expression was positively correlated with infiltrating levels of CD4 + and CD8 + T cells, macrophages, neutrophils and dendritic cells (DCs) in non-small cell lung cancer (NSCLC)." (PMID 33632211, 2021).
Aminoaciduria (4 papers, 2010 to 2025). An increased concentration of an amino acid in the urine. "The review highlighted 9 genes associated with aminoacidurias, including SLC3A1 (rBAT), SLC7A9 (bo,+AT), SLC6A19 (BoAT1), SLC7A7 (y+LAT1), SLC7A6 (y+LAT2), SLC36A2 (PAT-2), SLC6A20 (SIT-1), SLC6A18 (BoAT3), and SLC1A1 (EAAT3)." (PMID 41142409, 2025).
lupus (4 papers, 2019 to 2026). "Patients carrying biallelic pathogenic or likely pathogenic variants in SLC7A7 together with biochemical evidence of LPI were classified as having SLC7A7-associated monogenic lupus." (PMID 41821046, 2026). "This study aimed to investigate the clinical features, treatment strategies, and outcomes of pediatric patients with monogenic lupus caused by SLC7A7 mutations." (PMID 41821046, 2026). "A significant number of genes associated with autoinflammation and autoimmunity have been implicated in monogenic lupus, including SLC7A7." (PMID 35669728, 2022). "The mean age at SLE diagnosis in the SLC7A7-associated monogenic lupus group was 6.6 years, and patients were followed for an average of 5.5 years." (PMID 41821046, 2026). "RESULTS: Among pediatric SLE patients who underwent next-generation sequencing for suspected monogenic etiology, six were identified with biallelic SLC7A7 variants and biochemical evidence of lysinuric protein intolerance, accounting for 31.6% of all monogenic lupus cases in this cohort." (PMID 41821046, 2026). "For instance, patient 3C (MAN2B1 and SLC7A7) presented with predominant lung involvement which is an extremely rare manifestation as the first presentation of lupus." (PMID 31362757, 2019). "Although distinguished phenotypically, this included non-lupus-related features such as dysmorphism and developmental delay and infection arising as part of the complex phenotype of the causal variants identified (MAN2B1, SLC7A7, PTEN, STAT1)." (PMID 40465409, 2025). "SLC7A7 (solute carrier family 7 member 7) may be associated with monogenic lupus disease; however, only 2 cases of concomitant HCP and SLE have been reported." (PMID 35669728, 2022).
glioma (3 papers, 2021 to 2023). A benign or malignant brain and spinal cord tumor that arises from glial cells (astrocytes, oligodendrocytes, ependymal cells). "Analysis of data from PrognoScan revealed that increased SLC7A7 expression correlated with poor prognosis in several tumor types (prostate, colorectal, glioma, breast and lung cancer)." (PMID 33632211, 2021). "Notably, the analysis revealed that SLC7A7 expression was significantly correlated with prognosis in six types of cancer, including multiple myeloma, prostate, colorectal, glioma, breast and lung cancer." (PMID 33632211, 2021).
Hyperammonemia (3 papers, 2022 to 2025). An increased concentration of ammonia in the blood. "Molecular testing for hyperammonemia-related metabolic diseases identified two pathogenic variants in the SLC7A7 gene: c.1383_1384del (p.Ile461Metfs6) and c.726G > A (p.Trp242)." (PMID 41189639, 2025). "Patient with SLC7A7 (c.625 + 1 G > A) mutation suffered from profound glomerulonephritis with full-house glomerular deposits as well as hyperammonemia, metabolic acidosis and episodic conscious disturbance." (PMID 35964089, 2022). "While recessive disorder requires homozygous SLC7A7 defects to become phenotypic, the clinical phenotypes, presence of hyperammonemia, segregation analysis and the complete skipping of exon 4 revealed by complementary DNA analysis of Case 2 and 3 suggested a diagnosis of LPI." (PMID 35964089, 2022).
lung carcinoma (3 papers, 2021 to 2023). "A lung cancer cohort study (GSE31210) showed that high SLC7A7 expression was associated with poor overall survival (OS) and relapse-free survival (RFS)." (PMID 33632211, 2021). "SLC7A7 showed the same expression trend in breast, esophageal, head and neck, kidney and lung cancers in both the microarray and RNA-seq data." (PMID 33632211, 2021). "Nevertheless, in these databases we found consistent SLC7A7 expression in breast, esophageal, head and neck, kidney and lung cancer." (PMID 33632211, 2021). "In addition, our results indicated that SLC7A7 mRNA expression levels in colorectal, kidney, leukemia, sarcoma and lung cancer were significantly underexpressed compared to the corresponding normal tissues in some data sets." (PMID 33632211, 2021). "Therefore, we investigated whether SLC7A7 expression was related to immune infiltration levels in lung cancer by TIMER." (PMID 33632211, 2021). "However, the poor prognosis for lung cancer (OS: HR = 2.62, 95% CI 1.25–5.49, P = 0.0107; RFS: HR = 2.06, 95% CI 1.18–3.59, P = 0.0111) was correlated with higher SLC7A7 expression." (PMID 33632211, 2021). "To facilitate clinical application, in the lung cancer transcriptome, including 19,464 protein-coding genes, we extracted the three most relevant genes of B cell (CD19, TLR10, and FCRLA) and DC1 (ITGB2, LAPTM5, and SLC7A7), respectively." (PMID 34422829, 2021).